TMC1 (transmembrane channel like 1)
Diseases named in the same sentence as TMC1 in open-access papers (continued):
Sharing a sentence is not in itself a finding about the gene and the disease.
hearing loss (continued). "However, the mutation orthologous to p.M412K in murine Tmc1 has yet to been found in human hearing loss family since it has been reported in 2002." (PMID 24827932, 2014). "The TMC1 gene is the sixth most common cause of recessive hearing loss worldwide." (PMID 21917145, 2011). "TMC1 p.S647P appears to be a founder mutation for hearing loss in the Moroccan Jewish population." (PMID 21917145, 2011). "Comparison between TMC1 wt and M654V variant revealed differencesin pore architecture, lipid interactions, and electrostatic propertiesthat may collectively contribute to the pathogenic effects associatedwith hearing loss." (PMID 41288321, 2025). "Furthermore, our study could help direct the clinical diagnosis of hearing loss related to aberrant splicing of TMC1, LHFPL5, and TMIE." (PMID 33509951, 2021). "In Saudi Arabia, several gene mutations (e.g., GIPC3, ILDR1, W77R, MYO15A, TMC1, TMPRSS3, and DFNB67) have been identified in families and are associated with childhood hearing loss." (PMID 40918669, 2025). "The transmembrane channel-like protein 1 (TMC1) gene has been linked to autosomal recessive (DFNB7/11) and autosomal dominant (DFNA36) non-syndromic hearing loss, and it is a relatively common genetic cause of SNHL." (PMID 35407445, 2022). "The estimated prevalence of TMC1-associated hearing loss in the Japanese hearing loss cohort was 0.17% for all patients, 0.61% for ADNSHL and 0.07% for ARNSHL or sporadic hearing loss cases." (PMID 34523024, 2022). "Most of the successful functional recovery of mouse models for hereditary monogenic hearing impairment has involved genes that primarily contribute to the development and/or function of the postnatal mouse cochlea (e.g., Tmc1,60,61Vglut3,62Otof63,64)." (PMID 36034774, 2022). "DNFA36 results from GOF mutations of the tmc1 gene, whereas LOF mutations in both tmc1 alleles result in the autosomal recessive congenital DFNB7/B11 hearing loss disorder." (PMID 33192264, 2020). "The Beethoven allele (c.T1235A) of the transmembrane channel-like 1 (TMC1) gene is dominantly inherited and causes progressive hearing loss in mice." (PMID 30210291, 2018). "Somewhat remarkable were the present findings of a deep HFE genealogy upstream a Swedish river valley segregating with Wilson ́s disease and LQTS was also segregating with hearing loss caused by mutations in WHRN and TMC1 respectively." (PMID 29270100, 2017). "During the past ten years, three dominant mutations in TMC1 (p.D572N, p.D572H and p.G417R) from four DFNA36 hearing loss families have been reported, i.e., the mutation of p.D572N and p.D572H were found in North American families." (PMID 24827932, 2014). "Mutations in the autosomal genes TMPRSS3, TMC1, USHIC, CDH23 and TMIE are known to cause hereditary hearing loss." (PMID 24416283, 2014). "The interaction with TMC1 may be disrupted by the N-terminal truncation of CIB2 or several other missense mutations (p.E64D, p.F91S, and p.C99W) associated with hearing loss, which located in the central region of CIB2." (PMID 40076845, 2025). "Previously, we have generated iPSCs from a patient carrying TMC1 p.M418K mutation (M+/−) and a gene-corrected iPSC line (M+/C) using CRISPR/Cas9, as well as a normal control iPSCs (M+/+) from the patient’s normal son, who has no TMC1 mutation and hearing loss." (PMID 38167128, 2024). "Dominant and recessive mutations in TMC1, a gene encoding the pore-forming subunit of the hair cell mechanotransduction channel, cause DFNA36 and DFNB7/11, respectively, accounting for ∼2% of genetic hearing loss." (PMID 36574989, 2023). "Toward the clinical application of gene therapy for hereditary hearing loss, TMC1-associated ADNSHL is believed to be a good candidate, as the late-onset and progressive hearing loss phenotype can be stopped or slowed down by gene therapy prior to hearing deterioration." (PMID 34523024, 2022).
hearing loss (continued). "The transmembrane channel‐like 1 (TMC1, OMIM: 606706) gene is the sixth most frequent cause of hereditary hearing loss among the ARNSHL‐related genes based on worldwide case studies, following GJB2, SLC26A4, MYO15A, OTOF, and CDH23 (Hilgert, Smith, & Van Camp, 2009)." (PMID 29654653, 2018). "This speculation is consistent with the reported hearing loss types (such as high frequency progressive) in patients with the POU4F3, SLC17A8, TMC1, and CRYM mutations." (PMID 24676347, 2014). "With the exception of the p.R653C mutation in WFS1 and the p.D572N mutation in TMC1, the other five variants have not been previously reported to be associated with hereditary hearing loss." (PMID 25388789, 2014). "Several non-gene-edit methods have been applied for Tmc1-associated hearing loss." (PMID 38167128, 2024). "TMC1 (OMIM *606706) underlies dominant and recessive non-syndromic hearing loss at the DFNA36 and DFNB7/B11 loci and encodes for a protein expressed in cochlear and vestibular hair cells required for hair cell mechanoelectrical transduction." (PMID 34562878, 2021). "In our cohort, among 52 Moroccan Jewish individuals with hearing loss, not closely related to each other by self-report, 10 were homozygous for CX26 c.35delG, 10 were homozygous for TMC1 p.S647P, 6 were compound heterozygous for TMC1 p.S647P and p.R604X, and 9 were heterozygous for TMC1 p.S647P." (PMID 21917145, 2011).
autosomal recessive hearing loss (9 papers, 2013 to 2025). "Most of the TMC1 variants are responsible for autosomal recessive hearing loss, with only 8 variants reported as causative for DFNA36." (PMID 34523024, 2022). "TMC1 is a causative gene for both autosomal dominant non-syndromic hearing loss (DFNA36) and autosomal recessive non-syndromic hearing loss (DFNB7/11)." (PMID 34523024, 2022). "Mutations in TMC1 are a common cause of autosomal recessive nonsyndromic deafness, particularly in India, Pakistani, Turkish, and Tunisian families." (PMID 26822030, 2016). "The most remarkable finding was a gradient of gene expression changes in four genes (Pou4f3, Slc17a8, Tmc1, and Crym) whose mutations cause autosomal dominant deafness." (PMID 24676347, 2014). "Similarly, the TMC1 variant (p.Asp572Asn) accounts for about 4.4% (3/68) of progressive, postlingual autosomal dominant nonsyndromic hearing loss (ADNSHL) in the Chinese population." (PMID 32899707, 2020). "The TMC1 gene has previously been reported to cause autosomal recessive hearing loss." (PMID 29270100, 2017). "Especially for genes whose mutations cause autosomal dominant non syndromic hearing loss (Pou4f3, Slc17a8, Tmc1, and Crym) as well as genes important for cochlear function (Emilin-2 and Tectb), gradual expression changes may help to explain the various pathological conditions." (PMID 24676347, 2014).
sensorineural hearing loss (4 papers, 2014 to 2024). "TMC1 was identified by positional cloning of a gene underlying nonsyndromic sensorineural hearing loss and was shown to be one of two isoforms, along with TMC2, that is required for mechanoelectrical-transduction in hair cells of the mouse inner ear." (PMID 36191207, 2022).
nonsyndromic hearing loss (3 papers, 2014 to 2025). "TMC1 (OMIM: 606706) is a major contributor to autosomal recessive nonsyndromic hearing loss, with over 125 pathogenic variants identified to date, and just eight of those linked to autosomal dominant hearing loss." (PMID 40631239, 2025). "Of the 23 probands, six had mutations in DFNA genes [WFS1 (n = 2), COCH, ACTG1, TMC1, and POU4F3] known to cause autosomal dominant nonsyndromic hearing loss." (PMID 25388789, 2014).
lipoma (2 papers, 2019 to 2025). A benign, usually painless, well-circumscribed lipomatous tumor composed of adipose tissue. "Some components of the MET channel have been improved, such as transmembrane channel-like 1/2 (TMC1/2), transmembrane inner ear protein (TMIE), and lipoma HMGIC fusion partner-like 5 (LHFPL5)." (PMID 40076845, 2025). "In mice, lipoma HMGIC fusion partner-like 5 (LHFPL5) acts as an auxiliary subunit of the MET channel whose primary role is to correctly localize PCDH15 and TMC1 to the mechanotransduction complex." (PMID 32009898, 2019).
schwannomatosis (1 paper, 2022). The least frequent form of the rare genetic disorder neurofibromatosis. "A reproducible decrease in signal of a single control probe for the transmembrane channel like 1 (TMC1) gene on chromosome 9q21.13, was seen in a patient with thyroid cancer and schwannomatosis." (PMID 35723634, 2022).
Vertigo (1 paper, 2022). An abnormal sensation of spinning while the body is actually stationary. "Most of the TMC1-associated HL patients identified in this study did not have vestibular symptoms and only two patients had episodes of vertigo." (PMID 34523024, 2022).
cancer (2 papers, 2021 to 2022). A tumor composed of atypical neoplastic, often pleomorphic cells that invade other tissues. "The data from the FANTOM5, HPA, and databases showed concordant results that the TMC1 and TMC2 were almost not expressed in all analyzed tissues and cancer types." (PMID 34899684, 2021).
genetic disorder (1 paper, 2025). "However, in spite of the significant expression of TMC1 in numerous tissues other than the inner ear such as the kidney, placenta, testis, urinary bladder, brain, and prostate, no genetic disorder has been attributed to the presence of pathogenic variants in this gene, other than HL." (PMID 40100472, 2025).
tumor (1 paper, 2024). "Abundant Treg cells could infiltrate into tumor tissues and predicted poor prognosis 46, which was in line with the effects of TMC1 on clinical outcomes." (PMID 38706908, 2024).
TMC1 also shares sentences with these, for which no sentence is quoted: Hearing impairment (6 papers); inner ear disorder (2); auditory neuropathy spectrum disorder (1); glioma (1); hereditary hemochromatosis (1); Intellectual disability (1); long QT syndrome (1); nervous system tumors (1); Prader-Willi syndrome (1); pulmonary hypertension (1); Sensorineural hearing impairment (1); syndromic (1); thyroid cancer (1); thyroid disorders (1); Wilson ́s disease (1).